MC1R (melanocortin 1 receptor)
Diseases named in the same sentence as MC1R in open-access papers (continued):
Sharing a sentence is not in itself a finding about the gene and the disease.
melanoma (continued). "Finally, the performance improvement by including MC1R genotypes supports existing evidence that genetics can be used to improve melanoma risk prediction." (PMID 25003831, 2014). "Second, we demonstrated that adding MC1R genotype and indoor UV exposure data to a phenotypic melanoma risk model results in a small, but statistically significant increase in predictive ability, which was upheld when hair color measures were removed from the model (data not shown)." (PMID 25003831, 2014). "However, the influence of rare MC1R variants on melanoma predisposition has been poorly investigated which prompted us to study in detail the role of these variants in the French population." (PMID 24982914, 2014). "Finally, we observed that the expression signatures indentified in phenotypically normal cells carrying CDKN2A mutations or MC1R variants are maintained in skin cancer tumors (melanoma and squamous cell carcinoma)." (PMID 24742402, 2014). "To date, only three, preliminary, melanoma risk prediction models have included MC1R genotype." (PMID 24134749, 2013). "Melanocortin-1 receptor (MC1R) gene variants are very common and are associated with melanoma risk, but their contribution to melanoma risk prediction compared with traditional risk factors is unknown." (PMID 24134749, 2013). "Many pigmentation genes linked to melanoma in recent GWAS such as TPCN2, ASIP, KIT, NCKX5, TYR, IRF 4, OCA2 and TYRP1 have been linked to melanoma and some of them like MC1R have dual roles in pigmentation and immune responses but many other functions of these genes remain to be discovered." (PMID 23796690, 2013). "Moreover, the presence of an MC1R variant in addition to a CDKN2A mutation significantly increases the melanoma penetrance, decreasing the age at onset compared with individuals carrying a CDKN2A mutation alone." (PMID 24416617, 2013). "Previously, we observed a stronger association between MC1R and melanoma for men than women in this study (P = 0.005); in this analysis the multivariate OR for any R allele compared to wild-type consensus alleles was 4.20 (95% CI 1.75-10.10) for men and 2.44 (95% CI 1.31-4.56) for women." (PMID 24134749, 2013). "Specifically, individuals who were homozygous for MC1R mutant alleles had a significantly lower risk of melanoma-specific death in a series of 3060 cases from Europe and the United States (HR, 0.78; 95% CI, 0.65–0.94), implying that a functional MC1R pathway promotes melanoma progression in humans." (PMID 23555311, 2013). "Therefore, carriers of MC1R variants that correspond to the red hair, fair skin phenotype (V60L, R151C, R160W, and D294H) have a 2–4-fold increased risk of developing melanoma." (PMID 24416617, 2013). "The data are suggestive of a survival benefit for inherited MC1R variants in melanoma patients." (PMID 22325793, 2012). "In previous meta-analyses authors found evidence of a significant association between melanoma, red hair and fair skin and the five MC1R variants R151C, R160W, D294H, D84E and R142H, and suggested a possible role in melanoma development, via non-pigmentary pathways, for I155T and R163Q variants." (PMID 22862891, 2012). "In addition to the well-defined association of MC1R with melanoma, other low-penetrance melanoma risk alleles have been described in genes related to pigmentation, nevus count, immune responses, DNA repair, metabolism and the vitamin D receptor." (PMID 22978401, 2012). "Interestingly, MC1R-associated melanoma risk has been shown to increase with the number of variants in the genotype supporting the MC1R-associated susceptibility in our patients carrying two nonfunctional MC1R variants." (PMID 22978401, 2012). "Furthermore, individuals carrying two or more mutations in MC1R, a well-known low penetrance melanoma-predisposing gene, had a decreased MM risk if concurrently bearing the SLC45A2 protective variant." (PMID 21559390, 2011).
melanoma (continued). "In a genome-wide association (GWA) study of melanoma carried out by the GenoMEL consortium, association was confirmed between disease susceptibility and variants related to melanocortin-1 receptor (MC1R) and tyrosinase (TYR), and a new locus at chromosome 9p21 was identified." (PMID 22216283, 2011). "By contrast, in the DNA from all healthy donors and melanoma patients with skin type 1 we found several mutations previously associated with the red hair and fair skin phenotype as well as the loss-of-function of MC-1R." (PMID 20126537, 2010). "Moreover, MC-1R has been suggested to be critically involved in melanoma susceptibility since certain mutations in the MC-1R gene are strongly associated with increased melanoma incidence by sensitizing melanocytes to the cytotoxic effects of UV irradiation." (PMID 20126537, 2010). "Two MC1R germline variants classified as "R", Arg151Cys [odds ratio (OR), 6.4; 95% confidence interval (95% CI), 2.1-15.9] and Asp294 His (OR, 1.8; 95% CI, 1.1-5.3), were significantly associated with melanoma in our series." (PMID 19799798, 2009). "Further and more specific studies (based on better classification of the different skin phototypes and/or a more detailed evaluation of the general phenotypic characteristics) are required in order to define the role of such MC1R gene variants into the susceptibility to melanoma." (PMID 19799798, 2009). "Mutations in MC1R, a low-penetrance melanoma-predisposing gene, could also be involved in squamous cell skin cancers and in Hodgkin's disease." (PMID 18628759, 2008). "Functional changes in the human MC1R gene which causes a change in skin colour could lead to an increased susceptibility to ultra-violet radiation and hence higher levels of melanoma in humans." (PMID 18837980, 2008). "Interestingly, some MC1R polymorphisms may play a role in familial melanoma risk and it seems to be correlated to the number of inherited variants." (PMID 40869905, 2025). "MC1R has been found to promote the repair of UV-induced DNA damage whereas MC1R variants exhibit defects in their interaction with PTEN upon UV exposure so that they fail to inhibit the PI3K/ AKT signaling pathway driving the carcinogenic transformation of melanoma." (PMID 39417901, 2024). "Consequently, MC1R is being explored as a melanoma-specific diagnostic probe." (PMID 37790306, 2023). "Moreover, the absence of a comparison with a control group for the other genes beyond MC1R, due to the limited number of positive patients, hindered our ability to definitively establish the overall role of these genes in melanoma risk in the Brazilian population." (PMID 37958811, 2023). "Moreover, this group of MC1R variants (u alleles) showed a higher prevalence in our cohort when compared with the control group and may characterize high-risk melanoma patients in the Brazilian population." (PMID 37958811, 2023). "Interestingly, inherited MC1R variants are associated with survival benefits in melanoma patients." (PMID 37679505, 2023). "Thus, an increase in MC1R expression could portend a possible lower risk for subsequent melanoma development, as the authors of these studies suggest." (PMID 38256864, 2023). "Therefore, it can be hypothesized that deregulation of genes/proteins controlling MC1R signaling through this pathway should also modulate the risk of melanoma and the phenotype of melanoma cells." (PMID 35892921, 2022). "A large proportion of individuals of European ancestry, including New Mexico Hispanics, carry at least one MC1R gene variant that confers increased melanoma risk, although recent evidence found that the risk conferred by such variants may differ by specific Hispanic populations." (PMID 34439206, 2021). "In addition, variants of the MC1R gene increase the melanoma risk in CDKN2A mutation carriers." (PMID 34571969, 2021). "Germline MC1R variants may influence the mutational landscape of melanoma." (PMID 34356109, 2021).
melanoma (continued). "There are many polymorphisms of MC1R gene, which determine the different skin phenotypes; variants such as red hair and fair skin phenotype express low pigmentation, resulting in increased sensitivity to ultraviolet (UV) light and an increased risk of associated melanoma." (PMID 34447610, 2021). "In this randomized controlled trial, we examined whether receipt of precision prevention information communicating results of MC1R genotyping can improve sun-related behaviors among individuals with phenotypes that are associated with lower to average melanoma risk." (PMID 34201795, 2021). "Precision prevention information conveying MC1R testing results can increase the practice of some sun protection behaviors among at-risk individuals with limited melanoma risk phenotypes and may provide a cross-generational tool to counteract increasing incidence of melanoma." (PMID 34201795, 2021). "Interestingly, for the first time we have demonstrated that this balance is much closer to an irreversible dedifferentiation state in those melanoma cell lines, in which loss-of-function mutation in MC1R either is originally harboured or was acquired during the development of resistance." (PMID 31354817, 2019). "When patients were grouped according to the nevus density at the melanoma region, a high nevus density was significantly associated with young age at presentation, a high total body nevus count and density, and presence of one or more non-synonymous MC1R variants." (PMID 29228734, 2017). "Of note, their baseline model used age, sex, city of recruitment, and self-reported European ancestry as covariates, which are very different from our baseline model, suggesting that MC1R genotype may be a robust factor to help identify patients at increased risk for melanoma." (PMID 25003831, 2014). "To investigate whether the effect of the two main MC1R variant categories on melanoma susceptibility was independent of pigmentation traits, we conducted a multivariate analysis including the main clinical melanoma risk factors using logistic regression." (PMID 24982914, 2014). "Additionally, genetic variation at MC1R locus is also an important risk factor for melanoma." (PMID 24416617, 2013). "In a Greek study with 284 cases and 284 controls, Stefanaki and colleagues derived a melanoma risk prediction model containing phenotypic traits (except nevi was not available) and 8 single nucleotide polymorphisms (SNPs) from several genes that included the MC1R locus." (PMID 24134749, 2013). "In addition, some MC1-R variants have been associated to melanoma risk." (PMID 23634303, 2013). "Indeed, MC1R variants are associated with melanoma susceptibility in several study populations." (PMID 23537197, 2013). "Apart from MC1R, a significant number of low penetrance genes involved in various cellular pathways, such as pigmentation, cell cycle control, DNA repair, oxidation stress, apoptosis, senescence and melanocyte differentiation and migration have been implicated in melanoma susceptibility." (PMID 23393597, 2013). "Detection of two high-risk MC1R variants in our identical twins in the absence of CDKN2A and CDK4 mutations highlights the contribution of low penetrance genes, such as MC1R, in melanoma susceptibility, although additional known or as yet unknown genetic risk factors might be involved." (PMID 22978401, 2012). "However the relationship between some MC1R variants and melanoma also in darkly-pigmented European populations suggests that MC1R signaling may have an additional role in skin carcinogenesis beyond the UV-filtering differences between dark and fair skin." (PMID 22862891, 2012). "In contrast, loss-of-function mutations in the MC-1R gene impede the UV-induced up-regulation of α-MSH/MC-1R signaling and thereby might prevent the induction of tumor protection possibly accounting for the increased melanoma susceptibility in humans with red hair and fair skin." (PMID 20126537, 2010).
melanoma (continued). "Therefore, we investigated whether additional candidate genes, such as BRCA2 and MC1R, might play a role in melanoma susceptibility within such an isolated population." (PMID 19799798, 2009). "Reviews have noted that MC1R- and melanin-based probes “demonstrated promising and valid melanoma theranostic strategies”." (PMID 41008677, 2025). "The relationships among MC1R expression, clinical pathological parameters in melanoma patients were assessed using Chi-square and Fisher's precision probability tests." (PMID 40213552, 2025). "Interestingly, they found that inherited MC1R variants correlated with an improved overall survival rate only in women, suggesting that sex-dependent features may influence the role of specific genes involved in melanoma prognosis." (PMID 40869905, 2025). "In a murine melanoma model, the combination of melanocortin 1 receptor (MC1R)-targeted 212Pb-VMT01 with immune checkpoint inhibitors (ICIs; anti-CTLA-4 and anti-PD-1) proved superior in inhibiting tumour growth compared to treatment alone." (PMID 40303349, 2025). "Genetic polymorphism in MC1R, MC2R, MC3R, and MC4R genes is associated with risk of melanoma, familial glucocorticoid deficiency, obesity, and type 2 diabetes mellitus, respectively." (PMID 41002740, 2025). "The mutations in MC1R, MC2R, MC3R, and MC4R genes are associated with risk of melanoma, familial glucocorticoid deficiency, obesity, and type 2 diabetes mellitus, respectively." (PMID 41002740, 2025). "To this end, we employed a Transwell filter model in which human umbilical vein endothelial cells (HUVEC) were seeded in the upper chamber and cocultured with B16-F10 melanoma cells expressing MC1-R in the lower chamber." (PMID 41400998, 2025). "These structures can be tailored with ligands, antibodies, or peptides to target melanoma-specific biomarkers, such as BRAF mutations and MC1R, enabling selective drug delivery while minimizing off-target effects." (PMID 40142960, 2025). "Human melanotic and amelanotic melanoma arecharacterized by elevated levels of the G protein-coupled receptormelanocortin-1 receptor (MC1R)." (PMID 39895089, 2025). "Histochemistry score (H-score) determined the level of MC1R immunohistochemistry expression in melanoma." (PMID 40213552, 2025). "Treatment of B16F10 melanoma cells with oxyresveratrol suppressed melanogenesis through the down-regulation of the MC1R/cAMP/MITF signaling pathway." (PMID 40594379, 2025). "Our study is the first comprehensive analysis of MC1R germline variants in patients with LM/LMM in Utah, a region with an exceptionally high melanoma incidence." (PMID 40673485, 2025). "The first-in-human clinical trial evaluated the safety and biodistribution of two novel MC1R-targeted imaging tracers ([203Pb]VMT01 and [68Ga]VMT02) in stage IV melanoma patients to support the development of MC1R-targeted alpha-particle therapy." (PMID 40867277, 2025). "Genetic predisposition is significant as 5–12% of melanoma cases are familial and often linked to high-penetrance mutations in genes such as CDKN2A, BAP1, and MC1R involved in DNA repair, immune function, cell adhesion, transcription, and melanin production." (PMID 41283485, 2025). "Micelles can be functionalized with targeted ligands, antibodies, or peptides that recognize melanoma-specific biomarkers, such as overexpressed integrins or MC1R, enabling selective delivery to tumor cells while minimizing systemic toxicity." (PMID 40142960, 2025). "Germline variants in the melanocortin-1 receptor (MC1R) gene, which affect pigmentation and UV susceptibility, have been studied in melanoma." (PMID 40981345, 2025). "The survival time difference was statistically significant [MC1R expression in melanoma tumor tissue (MC1RT): median DFS, 12.83 vs. 17.53 months, χ2 = 5.395, P=0.0202; median OS, 16.47 vs. 21.77 months, χ2 = 5.082, P=0.0243." (PMID 40213552, 2025).
melanoma (continued). "In a murine melanoma B16 cell line, both endogenous and exogenous wild-type MC1R were demonstrated to be palmitoylated (at Cys315) upon activation." (PMID 40004137, 2025). "MC1R expression in normal adjacent to melanoma tissue (MC1RN): median DFS, 12.03 vs. 14.29 months, χ2 = 6.864, P=0.0088; median OS, 16.73 vs. 21.77 months, χ2 = 5.649, P=0.0175]." (PMID 40213552, 2025). "The melanocortin 1 receptor (MC1R)-targeted radiopeptide [212Pb]VMT01 effectively suppressed the growth of B16-F10 melanoma tumors." (PMID 40867277, 2025). "Patients with high MC1R expression in melanoma tissues exhibited a worse prognosis compared to patients with low MC1R expression." (PMID 40213552, 2025). "Radiolabeled peptides as radiopharmaceuticals targeting the melanocortin-1 receptor (MC1R) can selectively attack and eliminate melanomas." (PMID 39935431, 2025). "In human melanoma cell line HBL, binding of the ligand to MC1R causes the transactivation of c-KIT leading to the ERK1/ERK2 mitogen-activated protein kinase (MAPK) pathway, resulting in decreased melanin formation, which is independent of cAMP." (PMID 41002740, 2025). "MC1R has been shown to stimulate HLA-A2-restricted cytotoxic T lymphocytes, enhancing their ability to recognize peptides naturally processed on melanoma cells, further linking immune modulation to tumor immunity." (PMID 40547309, 2025). "In vivo studies using murine models with premature termination of the MC1R transcript have demonstrated accelerated melanoma development due to oxidative damage resulting from an increased pheomelanin-to-eumelanin ratio, even in the absence of UVR exposure." (PMID 40673485, 2025). "The molecular development of melanoma is mainly associated with mutations in the v-Raf (BRAF), NF-1 (neurofibromin 1), NRAS (neuroblastoma RAS viral oncogene homolog), and MC1R (melanocortin 1 receptor) genes." (PMID 40710294, 2025). "Gold nanoparticles (AuNPs) enable precise drug delivery and photothermal ablation by targeting melanoma-specific biomarkers, such as MC1R." (PMID 40142960, 2025). "Many well-known pigmentation genes were among the 150 most upregulated genes in the intradermal melanomas: Slc45a2, Tyrp1, Tyr, Pmel, Dct, Oca2, Mlana, Slc24a4, and Mc1r." (PMID 39804140, 2025). "A distinctive feature of MtMn is the elevated expression of the endocytic receptor Melanocortin 1 (MC1R) on the surface of human melanoma cells, making it a crucial tumor marker." (PMID 40843729, 2025). "Because the expression level of MC1R on melanoma cells is low, radiolabeled α-MSH analogs require HPLC purification for isolation from non-labeled peptides." (PMID 39828865, 2025). "Peptides targeting melanocortin 1 receptor (MC1-R) using α- and β-emitting radiopharmaceuticals have been labeled with radiolabels and shown effective melanoma growth control in mouse melanoma models." (PMID 40558363, 2025). "S-palmitoylation of melanocortin-1 receptor (MC1R) in melanoma is a classic example of tumour suppression by activation of tumour suppressor signals." (PMID 38485938, 2024). "The C’ dots were designed to display around 12 α-melanocyte-stimulating hormone (αMSH) peptide analogs for targeting the melanocortin-1 receptor (MC1-R) overexpressed on human melanoma cells (M21)." (PMID 39376728, 2024). "A recent study focused on developing a heterobivalent radiotracer targeting both the MC1R and integrin αvβ3, which play critical roles in melanoma progression and metastasis." (PMID 39598465, 2024). "While the MC1R expression level is much lower in healthy melanocytes, melanoma cells frequently overexpress it." (PMID 38256168, 2024). "Thus, variations in the melanocortin 1 receptor (MC1R), which can produce a fair-skinned and red-haired phenotype, are well-established drivers of melanoma risk in red-haired individuals but may also increase the risk in darker-haired or darker-skinned individuals." (PMID 39682251, 2024).